SMAD4 (SMAD family member 4)
Diseases named in the same sentence as SMAD4 in open-access papers (continued):
Sharing a sentence is not in itself a finding about the gene and the disease.
tumor (continued). "It was shown that TGF-β acting through SMAD4 and SMAD7 transduction enhances the recruitment of monocytes and activation of macrophages, suppresses the functioning of anti-tumor T-cells and generates immunosuppressive TIME facilitating immune evasion mechanisms and tumor progression." (PMID 39936166, 2025). "In SMAD4‐null BxPC‐3 cells, ITGAV KO reduced ERK phosphorylation, indicating an alternate signaling pathway and potential compensatory role for MAPK/ERK signaling in supporting tumor cell motility when TGF‐β/SMAD signaling is impaired." (PMID 40739706, 2025). "Preclinical studies suggest, that during tumor progression, key components of the canonical TGF-β pathway (e.g., SMAD2/3, SMAD4, TGFBR1/2) are often epigenetically downregulated via histone modifications, potentially leading to non-canonical pathway activation with pro-tumorigenic signaling routes." (PMID 40488800, 2025). "This, combined with impaired Smad4 function, may hijack the TGF-β pathway, shifting it from a tumor-suppressive to a pro-metastatic signaling cascade that drives EMT." (PMID 41472816, 2025). "In contrast, absence of SMAD4 in ILC1 and NK cells in mice caused NK cells to acquire an ILC1-like gene signature; these cells were unable to control tumor metastasis or viral infection." (PMID 40873573, 2025). "Whereas tumors harboring the control shRNA showed the expected reduction in tumor burden and fraction of Ki67+ cells following Smad4 reactivation, the p57-depleted tumors did not." (PMID 40999053, 2025). "Furthermore, pathways involved in tumour invasiveness and metastasis were also connected and presented in pLN+ OSCC, including clusters named ‘MET promotes cell motility’ and ‘SMAD2/SMAD3:SMAD4 heterotrimer regulates transcription’." (PMID 40038875, 2025). "SMAD4 is a pivotal signal transducer in the canonical Transforming Growth Factor-β (TGF-β) pathway, which forms a heterotrimeric complex with SMAD2/3 and translocates to the nucleus to suppress tumor progression." (PMID 40338154, 2025). "Deletion of SMAD4 from tumor cells does not prevent BMP4 from suppressing metastasis via a paracrine mechanism." (PMID 38689334, 2024). "In the context of CRC progression, the absence of SMAD4 hinders the infiltration of anti-tumor immune cells, thereby facilitating CRC recurrence and resistance to chemotherapy." (PMID 39439794, 2024). "Notably, SMAD4 inactivation occur in around 50%–60% of patients with PDAC, indicating that SMAD4 functions as a specific tumour suppressor in PDAC." (PMID 38789418, 2024). "We assessed the requirement for tumor cell expression of SMAD4 in mediating responses to BMP4, demonstrating that BMP4 is required for suppression of metastasis, regardless of the SMAD4 status of the tumor cells." (PMID 38689334, 2024). "There was a modest reduction in primary tumor growth in 231-HM-caBMPR1a-expressing cells in the presence but not in the absence of SMAD4." (PMID 38689334, 2024). "Recent studies have suggested that in the TME, mast cells marked by KIT and CPA3 can induce the release of TGF-β, activate Smad4 signal transduction, upregulate PAR-2 and ERK1/2 expression, and activate AKT signaling, thereby inhibiting tumor cell apoptosis and inducing resistance to gemcitabine." (PMID 38982491, 2024). "Overexpression of SMAD3, SMAD4, and SMAD5 indicates excessive stimulation of the TGFβ pathway, which may promote tumor proliferation and development." (PMID 39337574, 2024). "Smad4/DPC4, activated by TGF-β signaling, acts as a tumor suppressor gene." (PMID 38666907, 2024).
tumor (continued). "SMAD4, also known as DPC4 (Deleted in Pancreatic Cancer 4), belongs to a family of signal transduction proteins and it is considered a pivotal tumor suppressor gene involved in the TGF-β signaling pathway, which regulates cell growth, differentiation, and apoptosis." (PMID 39575418, 2024). "Therefore, the epistatic relationship between SMAD4 and STAT3 has implications for tumor aggressiveness, metastatic propensity, and therapeutic resistance." (PMID 38573819, 2024). "In SMAD4-knockdown tumors, SMAD4 was absent from the tumor cells but persisted in the mouse stromal cells." (PMID 38689334, 2024). "Hence, we provide proof for the existence of a RAC1b-TAp73α-SMAD4-BGN axis operating in both murine and human cells to provide tumor suppression by maintaining epithelial differentiation." (PMID 38255305, 2024). "BMP4 expression is required for suppression of metastasis regardless of the SMAD4 status of the tumor cells." (PMID 38689334, 2024). "Results demonstrated that CXCL10 exhibited low expression in tumor cells with Smad4 high expression group, showing a negative correlation between Smad4 and CXCL10 expression." (PMID 39346534, 2024). "Thus, current research on the relationship between SMAD4 and the PARP1 protein is primarily confined to the tumor development process." (PMID 39528473, 2024). "In contrast, BMP4 accelerated the growth of tumors with reduced SMAD4 expression, implicating a tumor growth-promoting role of non-canonical signalling." (PMID 38689334, 2024). "To distinguish the consequences of SMAD4-dependent (canonical) and SMAD4-independent (non-canonical) signalling, we generated several tumor lines with modified levels of SMAD4 and/or BMP4." (PMID 38689334, 2024). "In BMP4-expressing 231-HM tumors that lacked tumor-intrinsic SMAD4 expression, SMAD4 was still present in stromal cells, and canonical BMP4 signalling in the stroma was still likely to be functional." (PMID 38689334, 2024). "However, in pancreatic adenocarcinoma, SMAD4-dependent TGF-β signaling is often inactivated, diminishing its tumor-suppressive effects." (PMID 38666907, 2024). "Consistent with our hypothesis, when SMAD4 activity was reduced by two different shRNA constructs, enforced BMP4 accelerated tumor growth in the 231-HM tumor model." (PMID 38689334, 2024). "Altogether, our data on human PDAC clearly suggest that the absence of TAp73 impairs TGF-β signaling toward the tumor-suppressing SMAD4 dependent pathway." (PMID 37568607, 2023). "Patients with increased/preserved SMAD4 and RUNX3 expression in either the tumor epithelium (HR = 0.34, 95% CI 0.18–0.66, p = 0.001) or the stromal compartment (HR = 0.34, 95% CI 0.2–0.57, p < 0.001) had significantly better prognoses compared to those with decreased/lost expression." (PMID 36900240, 2023). "Alterations in the tumor immune microenvironment can also lead to primary drug resistance, such as the finding that tumor-associated macrophages can be recruited due to the effect of HDAC5 on chemokine, mediating SMAD4-dependent and KRAS-independent PDAC tumor growth." (PMID 36675641, 2023).
tumor (continued). "Given that tyrosine kinases are often constitutively active in various cancers and drive oncogenesis and may act to inhibit TGF-β tumor-suppressive signaling, we screened tyrosine kinases for tyrosine phosphorylation of the key TGF-β signal transducer Smad4." (PMID 36959211, 2023). "From tumor tissues of patients with resectable PDAC enrolled to a clinical trial, we demonstrated that the combination of KLF10 and SMAD4 expression in tumor tissues may help select those who may benefit the most from additional radiotherapy." (PMID 37958386, 2023). "Increased Smad4 could inhibit the influence and regulation of TGF‐β on cell biological activities and plays a tumour suppressor role." (PMID 37563869, 2023). "Stromal IRS-1 was moderately (0.4 < r < 0.6) correlated with tumor epithelial and stromal SMAD4, and tumor epithelial and stromal RUNX3, indicating a possible link between stromal IRS-1 and pathways involving activated SMAD4 and RUNX3." (PMID 36900240, 2023). "Patients with and without SMAD4 alterations were comparable with respect to age, sex, T-stage, N-stage, and tumor grade." (PMID 38002058, 2023). "Furthermore, overexpression of TRIM47 accelerates many tumor progressions by regulation of aerobic glycolysis, Wnt/β-catenin pathway, PI3K/Akt pathway, and degradation of SMAD4." (PMID 36906594, 2023). "In addition, SMAD4/DPC4 deletion induced the upregulation of the glycolytic enzyme PKG1 and the leucine zipper protein FOSL1, enhancing glycolysis and aggressive tumour behaviour and promoting lung metastasis." (PMID 37685308, 2023). "A total of 31% (9/29) of cases had SMAD4/DPC4 inactivated in high-grade tumours (Pan in-3), while no inactivation was found in the remaining 159 low-grade lesions (Pan in-1 and 2)." (PMID 37685308, 2023). "This study suggests that SMAD4/DPC4 is not an absolute tumour suppressor in PDAC but rather has a positive effect on the immune microenvironment of tumours." (PMID 37685308, 2023). "In brief, these findings showed that circLDLRAD3 could execute its tumour suppressor effect on OSCC cell proliferation and migration via miR‐558/Smad4 axis." (PMID 37563869, 2023). "In addition, active ALK can phosphorylate SMAD4 at Tyr95, disable the DNA-binding activity of SMAD4 and then abrogate TGF-β-mediated tumor suppression responses." (PMID 36167821, 2022). "Interestingly, tumor invasion and migration are also mediated via the TGF-β/SMAD4 signaling pathway." (PMID 35807116, 2022). "TGF-β type III receptor (TGFBR3) is an important part of TGF-β signal transduction, which acts as tumor suppressor in tumor and stromal cells through SMAD4-dependent and non-dependent manner during head and neck squamous cell carcinogenesis." (PMID 36090900, 2022). "These miRNAs are important negative regulators of the expression of tumor suppressor genes such as PTEN (phosphatase and tensin-like protein), TGFBR2 (transforming growth factor beta receptor 2), SMAD4 (mothers against decapentaplegic homolog 4), and p21 (cyclin-dependent kinase 2 inhibitor)." (PMID 35205839, 2022). "LOH in chromosome 18q containing tumor suppressor genes SMAD2, SMAD4, and DCC is also common as these genes are transcriptional mediators of the transforming growth factor (TGF)-β signaling pathway, which regulates cell growth, differentiation, and apoptosis, and promotes MYC activation." (PMID 35975243, 2022). "Therefore, in terms of regulating the tumor microenvironment, ADRB2, SMAD4, FCER2 and PDCD1 had vital predictive significance in the immunotherapy of NSCLC." (PMID 36005189, 2022). "Meanwhile, SMAD4 inactivation in PAAD could promote upregulated expression of PGK1 and enhance glycolysis and tumor invasiveness." (PMID 35795552, 2022). "Transcription of a gene coding for ‘Mothers against decapentaplegic homolog 4’ (SMAD4) was significantly downregulated in two out of three patients tested (no significant change in the third tumor specimen)." (PMID 35681633, 2022).
tumor (continued). "In CRC lacking SMAD4, BMPR2 can bind to LIM domain kinase 1 to activate the Rho/Rho-associated protein kinase (ROCK) pathway to promote tumor invasion and metastases." (PMID 35805024, 2022). "have suggested that the deletion of Smad4 in CRC promotes the expression of CCL15 and recruits more CCR1+ TANs and matrix metalloproteinase-9 to the metastatic site to form the premetastatic niche of disseminated tumor cells." (PMID 35912260, 2022). "A similar relative abundance of SMAD4–201 transcript was found in the majority of analyzed human tumor tissue samples, and it was averagely 20% lower in non-malignant in comparison to malignant tissue samples (p = 0.001)." (PMID 35034624, 2022). "A set of human samples taken from patients with CRC was used to analyze the differences in SMAD4–201 expression levels between tumor and non-tumor tissue." (PMID 35034624, 2022). "PDX formation in the flank of the mice could already be observed two weeks after subcutaneous inoculation with Luciferase-eGFP+ SMAD4(-) ISO76A cells, while a tumor volume of 1500 mm3 was reached after a median period of eight weeks." (PMID 35902550, 2022). "Taking advantage of MMP7 deficient mouse models, the EMT-related transcription factors, including Snail, Slug, Twist, Smad4 and ZEB1, and the several ECM components, including Fibronectin, Collagen, Vimentin and N-cadherin, were reduced in tumor progression and fibrotic disease model." (PMID 35659367, 2022). "SMAD4 is a key transcription factor of TGF-β signaling and a tumor suppressor." (PMID 35935996, 2022). "In summary, these data suggest that tumor‐intrinsic Smad4 expression downregulated antigen presentation machinery gene expression and partially reduced DNA damage and IFN‐I pathway activity, together attenuated Smad4KO‐mediated tumor inhibition." (PMID 35064757, 2022). "For SMAD4, as well as for pSMAD2, a typical staining pattern was observed with an intense positive nuclear staining on the tumour edges, and a weak/negative staining pattern towards the centre of the tumour fields." (PMID 35756604, 2022). "Additionally, SMAD4 overexpression can inhibit CRC growth by inhibiting VEGF-A and VEGF-C expression in the HCT116 cell line and an promote tumor cell apoptosis in HCT116 cells and nude mouse models." (PMID 36430910, 2022). "Accordingly, a low dose of recombinant IFNγ strongly upregulated PD-L1 in tumor cells, irrespective of the presence of TGFβ or SMAD4." (PMID 35155243, 2022). "Here, we found that the tumor growth of Smad4 WT PDAC cells in vivo was not affected by the depletion of immune cells including CD4+, CD8+ T cells or NK cells, suggesting poor immunogenicity of the PDAC tumor cells." (PMID 35064757, 2022). "Of note, PGK1 expression is heterogeneous across human PDAC samples, with both the total levels of the protein as well as its intracellular localisation varying, suggesting that within SMAD4-negative tumours there are differences in metabolic states." (PMID 36088504, 2022). "However, other reports have shown that, in advanced tumors, intact SMAD4 facilitates EMT and TGFβ-dependent tumor growth." (PMID 36088360, 2022). "We demonstrated that patients without SMAD4 expression at the central lesion or tumor invasion front have poorer OS than those with SMAD4 expression at any site." (PMID 36088360, 2022).
tumor (continued). "The results of our study, coupled with our findings on the correlation between Sniad4 and TIF1-γ expression and tumor stage in clinicopathological samples, suggest that later studies should also focus on the relationship between TIF1-γ and ubiquitinated Smad4 protein." (PMID 35251569, 2022). "Thus targeting BMP2/4 in an in vivo PDX model of SMAD4(-) EAC cells decreases chemoresistance and induces tumor cell death." (PMID 35902550, 2022). "Enhanced CD80 expression on DCs induced by tumor cell coculture was significantly attenuated, but not completely reversed, in DCs cocultured with Smad4 re‐expressed tumor cells." (PMID 35064757, 2022). "SMAD4 has a principal role in TGF-β (Transformis growth factorβ)-induced epithelial to mesenchymal transition (EMT) as a key factor in gaining cancer stem cell (CSC) features and tumor aggressiveness." (PMID 34012911, 2021). "miR-455-5p may exert tumor promoting roles by inhibiting the expression of CDKN1B and influencing cell cycle and miR-1255a may be oncogenic by down-regulating SMAD4 and affecting TGF-β signaling pathway, which resulted in poor prognosis." (PMID 34707990, 2021). "The anti-tumor effect of MSCs-derived exosomes was underpinned by concurrent inhibition of factors including EGFR, NF-kappaB and mothers against decapentaplegic homolog 4 (SMAD4)." (PMID 35095909, 2021). "Five patients were excluded as they were not treated with the maximum dose of HCQ during the dose escalation phase, 10 patients did not have SMAD4 staining performed, and 2 patients were not resected and therefore had no tumor available for SMAD4 staining." (PMID 34002944, 2021). "Previous studies have already proved the regulation function of SMAD2, SMAD4, and TGFBR2 in cancers, and these genes were also found related with miRNAs that strongly correlated with tumor features, indicating the potential function and clinical utility in immunotherapy." (PMID 34722540, 2021). "Meanwhile, TGFβ had resulted in EMT and promoted tumor progression when SMAD4 was absent in tumor cells." (PMID 34048444, 2021). "However, in the late phase, SMAD4 is inactivated whereas TGFβ expression is upregulated leading to PI3K/Akt, Ras/ERK, p38MAPK, and Rho/GTPase pathway activation and subsequent tumor progression." (PMID 33889150, 2021). "Our results suggest that the Smad4 and TAK1-TRAF6-P38 MAPK signaling pathways are essential for TGFβ-induced autophagy and provide specific targets for the inhibition of TGFβ in tumor cells that utilize autophagy in their epithelial-mesenchymal transition program." (PMID 34760883, 2021). "Hepatoma carcinoma cell-derived exosomal miR210 might enter endothelial cells, and affect SMAD4 and STAT6 to promote tumor angiogenesis." (PMID 34098850, 2021). "Inactivation or low expression of Smad4 may affect TGF-β signal transduction and participate in tumor formation." (PMID 33794845, 2021). "miR-27a acts as an oncogen by repressing the expression of the tumor suppressors SMAD2 and SMAD4." (PMID 33498521, 2021). "On the other hand, one group reported a reversed relationship between Smad4 and tumor grading, i.e., Smad4 immunohistochemical staining decreases progressively with tumor grade, however without the correlation with patient’s outcome." (PMID 34501347, 2021). "Because of the dual roles of SMAD4 in cancer cells, agents have been designed to inhibit rather than activate TGF-β in SMAD4-deficient tumours." (PMID 33008426, 2020). "The enrichment in the signature associated with TGF-β activation and EMT demonstrated the activity of the tumor suppressor gene and, indirectly, that the nS/MAR technology can provide the sustained expression of functional SMAD4 throughout hundreds of cell divisions." (PMID 32420409, 2020).